PLAU (plasminogen activator, urokinase)
Diseases named in the same sentence as PLAU in open-access papers (continued):
Sharing a sentence is not in itself a finding about the gene and the disease.
lung adenocarcinoma (5 papers, 2016 to 2025). A carcinoma that arises from the lung and is characterized by the presence of malignant glandular epithelial cells. "We observed PLAU was downregulated with RIG-I activation whereas it was upregulated in the lung adenocarcinoma endothelial cells." (PMID 37100811, 2023). "To estimate the survival function of ISG15, MMP1, TRPA1, KRT19, and PLAU, we performed KM plotter analysis generated for groups of lung adenocarcinoma patients based on their expression levels." (PMID 35354498, 2022). "Lung adenocarcinoma patients with high expression levels of ISG15, MMP1, TRPA1, KRT19, and PLAU (red line) were significantly associated with poor survival rates (log rank P value: 2.3e-07, 0.00034, 0.00037, 0.00057, and 0.023, respectively) as compared to those with low expression (black line)." (PMID 35354498, 2022). "Taken together, our results suggest that TSPX may suppress the development and/or progression of lung adenocarcinoma by downregulating AREG, BIRC3, DKK1, EREG, FOSL1, MYC, and PLAU, which could exacerbate lung adenocarcinoma, and upregulating the tumor suppressor CACNA2D2." (PMID 39858622, 2025). "The expression levels of AREG, BIRC3, DKK1, EREG, FOSL1, MYC, and PLAU are negatively correlated with the survival ratio, and are significantly higher in the TSPX-low lung adenocarcinoma samples, compared to TSPX-high lung adenocarcinoma samples." (PMID 39858622, 2025). "Collectively, our findings suggest that pathologic downregulation of TSPX in NSCLC, especially in lung adenocarcinoma, results in upregulation of AREG, EREG, FOSL1, MYC, and PLAU, thereby potentiating the EGFR signaling pathway and leading to the initiation and/or exacerbation of cancer development." (PMID 39858622, 2025).
oral squamous cell carcinoma (5 papers, 2019 to 2024). "Another study reported that the downregulation of PLAU reduces the EMT-related genes expressed in the oral squamous cell carcinoma (OSCC) cell line leading to cessation of cell migration and invasion." (PMID 39149564, 2024). "Of all primary tumor types, Oral Squamous Cell Carcinoma (OSCC) and Pancreatic Adenocarcinoma (PAAD) express the highest levels of F3, PLAU, and SERPINE1 mRNA (encoding the uPA inhibitor PAI-1, Plasminogen Activator Inhibitor-1)." (PMID 36900323, 2023). "Similarly, Zhao found that PLAU, CLDN8 and CDKN2A could predict OS using gene expression profiles of GSE13601, GSE30784, GSE37991 and TCGA in oral squamous cell carcinoma." (PMID 30937621, 2019).
osteosarcoma (5 papers, 2017 to 2023). A usually aggressive malignant bone-forming mesenchymal neoplasm, predominantly affecting adolescents and young adults. "Upregulation of EGR1 in QPD megakaryocytes is interesting as EGR1 has been implicated in the regulation of PLAU in osteosarcomas." (PMID 28301587, 2017). "PLAU transcript levels were significantly decreased in UHRF1 KO osteosarcoma cells and subcutaneous xenografts, with an average 2.2-fold decrease compared to VC cell-derived tumors (P = 0.038)." (PMID 36068209, 2022).
platelet disorder (5 papers, 2017 to 2025). "PLAUR is the receptor of plasminogen activator (PLAU), which participates in various physiological functions such as wound healing and is also associated with rheumatoid arthritis, Quebec platelet disorder, and tumor angiogenesis and metastasis." (PMID 40224547, 2025). "Interestingly, one of the candidate variants identified was in the canonical splice site of a key player of the coagulant pathway, PLAU, that has been previously related to bleeding disorders, tandem duplication of this gene is related to Quebec platelet disorder (MIM #601709) in a dominant model." (PMID 35725860, 2022). "Finally, it is worth noting that moderately reduced platelet count is a feature of a congenital platelet disorder characterized by a gain-of-function fibrinolysis defect due to increased expression and storage of urokinase plasminogen activator (PLAU) during megakaryocyte differentiation." (PMID 28787443, 2017).
asthma (4 papers, 2009 to 2024). "Our investigation revealed that six of these genes (PDE4B, SPRR2B, ADCY2, KIF3A, DNAH5, and PLAU) were located in chromosomal regions that had been previously linked to asthma or other allergic disease phenotypes and had been shown to be regulated during allergic inflammation." (PMID 21912604, 2011). "KEGG functional analysis revealed that MMP1 was enriched in autoimmune thyroid disease and cell adhesion molecule cams, SAA1 was enriched in autoimmune thyroid disease and cell adhesion molecule cams, and PLAU was enriched in asthma and the citrate cycle." (PMID 39744064, 2024). "Interestingly, PLAU and PAI-1 expression are also elevated in sputum from asthma and COPD subjects suggesting the plasminogen system may be augmented in these diseases." (PMID 19878584, 2009).
glioblastoma (4 papers, 2015 to 2024). The most malignant astrocytic tumor (WHO grade IV). "PLAU was shown to participate in the migration and invasion of glioblastoma." (PMID 34093649, 2021). "PLAU inhibitors are being actively explored as anticancer strategies in glioblastomas and may have antiangiogenic properties." (PMID 26083629, 2015). "There, genes with a higher expression in glioblastoma compared to astrocytoma were VEGFA, 4EBP1, CCL2, PLAU (uPA), CXCL8 (IL8), CXCL10 (IP10), CASP8, HGF, LIF, CD40, CDCp1, TNFRSF11B (OPG), CD274 (PD-L1), IL6, CXCL1, CCL20 (MIP3α), CCL8 (MCP2), CD244, MMP1, TNFRSF9, CXCL6, MMP10, FGF5)." (PMID 35301393, 2022).
metastatic tumors (4 papers, 2022 to 2023). "Thus, we suggest that targeting BOP1 and/or PLAU can be advantageous against both primary and metastatic tumors." (PMID 36203433, 2022). "However, key MMP remodeling-associated genes PLAU and MMP10 and basal cell marker KRT19 were uniquely shared upregulated genes in metastatic tumors (MET and PRI+)." (PMID 35480116, 2022). "The highest differentially expressed genes in metastatic (MET and PRI+) versus non-metastatic tumors (PRI-) and SES included PLAU, PLAUR, MMP1, MMP10, MMP13, ITGA5, VEGFA, and various inflammatory cytokine genes." (PMID 35480116, 2022).
rheumatoid arthritis (4 papers, 2005 to 2025). A chronic, systemic autoimmune disorder characterized by inflammation in the synovial membranes and articular surfaces. "PLAU, also known as urokinase-type plasminogen activator, exerts several biological effects in various physiological and pathological processes such as keratinocyte proliferation, airway inflammation and rheumatoid arthritis." (PMID 40143204, 2025).
Venous thrombosis (4 papers, 2009 to 2025). Formation of a blood clot (thrombus) inside a vein, causing the obstruction of blood flow. "Moreover, venous thrombosis resolution and vein wall healing are mediated by leukocytes, particularly macrophages, and their associated chemokines, tissue-type or urokinase-type plasminogen activator (PLAT or PLAU), matrix metalloproteinases (MMPs), and proinflammatory cytokines." (PMID 32117207, 2019).
bleeding disorders (3 papers, 2009 to 2022). "As other hematopoietic lineages, and the other duplicated gene, C10orf55, had not been studied in QPD, we further explored the nature of the PLAU regulatory defect in this bleeding disorder." (PMID 28301587, 2017). "Importantly, these data provide new direct evidence that a megakaryocyte and PLAU specific defect in gene regulation underlies the marked over-expression of PLAU by the disease chromosome in QPD, which is the hallmark feature of this unique bleeding disorder." (PMID 28301587, 2017).
Brain Tumors (3 papers, 1998 to 2022). "PLAU and its receptor (PLAUR/uPAR) are mainly involved in invasion and cell proliferation, and their increased expression is correlated with a wide range of human diseases, including autism, Alzheimer’s, AIDS dementia, cerebral malaria and brain tumors." (PMID 27846841, 2016).
liver diseases (3 papers, 2012 to 2026). "Although no literature has shown so far that PLAU, FGF5, and IL24 affect HIRI by regulating immune cell infiltration, studies have reported the important regulatory roles of these two genes in the immune microenvironment and immune response in liver disease." (PMID 40705804, 2025).
liver fibrosis (3 papers, 2015 to 2021). "In cattle, liver fibrosis has been proposed as a downstream effect of upregulated TNF and IL1B, which would activate the genes that were also upregulated in the bovine study, i.e., IL6, PLAU, SERPINE1, TNFRSF1A, SOCS1, and CTSB." (PMID 34616397, 2021).
Obesity (3 papers, 2019 to 2024). Accumulation of substantial excess body fat. "Taken together, we conclude from these results that the deleterious effect of dietary beef tallow on disorders connected to obesity may be triggered by impaired fibrinolysis (downregulation of the PLAU gene) and increased coagulation (increased expression of F3 and decreased expression of THBD)." (PMID 31756991, 2019). "The lack of differences in the gene expression of placental ADAM17, PLAU, and IGF2 between the three groups suggests that these genes would not be affected by obesity." (PMID 37408866, 2023).
pancreatic adenocarcinoma (3 papers, 2022 to 2023). "Furthermore, survival analysis of these genes was conducted with the Kaplan-Meier method, and as a result, MYLK, SOCS3, STAT5B, and PLAU genes were obtained with the highest mortality rate for pancreatic adenocarcinoma (PAAD) patients." (PMID 35928368, 2022).
squamous cell carcinoma (3 papers, 1996 to 2023). A carcinoma arising from squamous epithelial cells. "In a human clinical trial of PD-1 checkpoint inhibitor treatment of two types of squamous cell carcinoma, high expression of TSK-specific genes ITGB1 and PLAU correlated with significantly reduced progression-free survival (p = 0.0137)." (PMID 32579974, 2020). "Notably, previous research has established PLAU and ITGA5 as critical biomarkers for various types of squamous cell carcinoma." (PMID 37510272, 2023).
thyroid cancer (3 papers, 2022 to 2024). "Thus, mechanistically, PLAU is involved in the regulation of pathways related to the immune microenvironment of thyroid cancer, and it is closely associated with the development of thyroid cancer." (PMID 35141223, 2022). "Given that the previous analysis suggested a possible role for PLAU in the immune response, in this section we explore the possible role of PLAU in the immune microenvironment of thyroid cancer." (PMID 35141223, 2022). "Meanwhile, the transcription level of PLAU was higher in thyroid cancer, which indicates a poor prognosis." (PMID 35141223, 2022). "PLAU and MMP-1 primarily mediate the prometastatic activity of NF-κB in thyroid carcinomas, given that they are involved in cancer cell migration and invasion, especially in advanced thyroid malignancies." (PMID 39519020, 2024).
colon adenocarcinoma (2 papers, 2014 to 2016). "Reports suggest that miR-193a expression inhibits tumourigenicity and invasiveness by directly targeting KRAS and plasminogen activator urokinase (PLAU), respectively, with these two factors highly expressed in human colon adenocarcinomas." (PMID 27590724, 2016).
dementia (2 papers, 2023 to 2024). Loss of intellectual abilities interfering with an individual's social and occupational functions. "Our analysis validates the interdependence of AD, dementia, and Parkinson’s disease through various common genes (i.e., A2M, ABCA7, PLAU, PSEN2, and MPO)." (PMID 38790243, 2024).
endometriosis (2 papers, 2013 to 2022). The growth of functional endometrial tissue in anatomic sites outside the uterine body. "PLAU is upregulated in ovarian endometrioid carcinomas from women with concurrent endometriosis, suggesting PLAU upregulation may promote malignant transformation in endometriosis." (PMID 36153585, 2022).
head and neck cancer (2 papers, 2021 to 2024). A primary or metastatic malignant neoplasm affecting the head and neck. "HPV positivity is well-accepted as a strong survival favorable factor in head and neck cancer patients, which indirectly supports that low expression of PLAU predicts a better survival in HNSCC patients." (PMID 33520474, 2021).
Hyperglycemia (2 papers, 2022 to 2025). An increased concentration of glucose in the blood. "Our study demonstrates that AQR/PLAU is a novel but critical signaling axis mediating hyperglycemia-induced cellular senescence that contributes to diabetic vascular complications." (PMID 35270021, 2022).
ischemic stroke (2 papers, 2022 to 2025). A stroke disorder caused by obstruction of blood flow to the brain, due to thrombotic (local blood clot formation) or embolic (due to a blood clot or other material traveling from another site) event. "Chrysin exerts anti-inflammatory effects in ischemic stroke by targeting plasminogen activator urokinase (PLAU) and inactivating the NF-κB pathway." (PMID 41322306, 2025).
liver cancer (2 papers, 2020 to 2023). An epithelial or non-epithelial malignant neoplasm that arises from the liver. "In liver cancer, there are not many studies related to the PLAU gene." (PMID 36838613, 2023).
non-small cell lung carcinoma (2 papers, 2017 to 2025). A group of at least three distinct histological types of lung cancer, including non-small cell squamous cell carcinoma, adenocarcinoma, and large cell carcinoma. "Our analysis was consistent with similar analysis completed in human non-small cell lung cancer in which PLAU, PLAUR, IL1R2, CD274, OSM, and CXCL8 were reported to be significantly enriched in TANs relative to circulating neutrophils." (PMID 39932553, 2025).
oral cancer (2 papers, 2021 to 2022). "PLAU is found to be upregulated in cisplatin-resistant oral cancer cell lines." (PMID 36203433, 2022).
ovarian tumor (2 papers, 2012 to 2021). "Further, PLAU overexpression is commonly observed in ovarian tumors and is associated with higher stage and grade as well as poor outcomes, demonstrating potential biologic mechanisms linking NE to ovarian carcinogenesis." (PMID 34253763, 2021).
Quebec platelet disorder (2 papers, 2021 to 2025). "In humans, the gain-of-function defect in fibrinolysis due to the tandem duplication of the PLAU gene causes the development of the Quebec platelet disorder (QPD), an autosomal dominant disease." (PMID 34354133, 2021).
type 2 diabetes (2 papers, 2019 to 2024). "Finally, single-gene validation and receptor operating characteristic analysis revealed that four of these genes (MMP12, PLAU, KRT14, and DKK1) may be involved in the common pathogenetic mechanism of adamantinomatous craniopharyngioma and type 2 diabetes." (PMID 38848397, 2024).
Alzheimer disease (1 paper, 2019). A progressive, neurodegenerative disease characterized by loss of function and death of nerve cells in several areas of the brain leading to loss of cognitive function such as memory and language. "There have been several reports suggesting associations between polymorphisms in the PLAU gene and the incidence of Alzheimer’s disease." (PMID 31756991, 2019). "Moreover, the PLAU gene has been identified as related to Alzheimer’s disease via a network and pathway-based approach." (PMID 31756991, 2019).
aortic valve calcification (1 paper, 2025). "Combining bulk RNA-seq and scRNA-seq, it was found that MMP9 and PLAU are mainly related to the immune activation of monocytes and macrophages in aortic valve calcification, providing new insights for early AS treatment." (PMID 41322480, 2025).
bile duct cancer (1 paper, 2024). "A previous study found that human PLAU could activate the NF-κB signaling pathway and participate in the development of bile duct cancer." (PMID 38440983, 2024).
Cachexia (1 paper, 2023). Severe weight loss, wasting of muscle, loss of appetite, and general debility related to a chronic disease. "As a result, the expression level of PLAU was significantly positively correlated with the cachexia score." (PMID 36937875, 2023).
cervical squamous cell carcinoma (1 paper, 2025). A squamous cell carcinoma arising from the cervical epithelium. "Furthermore, compared to normal cervical tissues, the protein expression of FN1, ICAM1, and PLAU was significantly upregulated in cervical squamous cell carcinomas." (PMID 40141137, 2025).
chondrosarcoma (1 paper, 2012). A malignant cartilaginous matrix-producing mesenchymal neoplasm arising from the bone and soft tissue. "In particular, upregulation of urokinase (PLAU) was associated with an increased rate of metastasis and a decreased metastasis-free survival in 114 cases of chondrosarcoma of bone." (PMID 22448124, 2012). "They found that the high-grade dedifferentiated components of the tumors—but not the low-grade components of the same tumors, nor conventional chondrosarcomas-exhibited robust, diffuse coexpression of PLAU and PLAT." (PMID 22448124, 2012).
diabetes (1 paper, 2016). "Hence, chronic inflammation associated with diabetes could be one of the reasons for overexpression of PLAU in diabetes patients." (PMID 27781209, 2016).
dystroglycanopathy (1 paper, 2014). "This gene has only one high-confidence association in the STRING database, with PLAU (plasminogen activator, urokinase), which itself has 10 high-confidence associations to other genes, none of which is related to type A muscular dystrophy-dystroglycanopathy." (PMID 25078397, 2014).
follicular thyroid cancers (1 paper, 2022). "Interesting, PLAU also functioned as oncogene in papillary and follicular thyroid cancers." (PMID 35141223, 2022).
hyperlipidemia (1 paper, 2021). "Importantly, A2M, APP, CLU, IGF2 and PLAU are not among the hyperlipidemia associated genes, they are retrieved only after obtaining the disease module with DIAMOND." (PMID 34824199, 2021).
IgA nephropathy (1 paper, 2016). "By overlap, we found three genes, JUN, FOS, and PLAU were simultaneously participated in aging and inflammation, and were also previously reported to be related to IgA nephropathy." (PMID 27127888, 2016). "Only PLAU, JUN, and FOS were related to DNA damage, telomere dysfunction-induced aging markers, neutrophil function and IgA nephropathy." (PMID 27127888, 2016).
invasive breast carcinoma (1 paper, 2022). A carcinoma that infiltrates the breast parenchyma. "Gabriel found that PLAU was involved in the metastasis of invasive breast cancer, and had an unexpected complexity of transcription." (PMID 35141223, 2022).
ischemia (1 paper, 2023). A hypoperfusion of the BLOOD through an organ or tissue caused by a PATHOLOGIC CONSTRICTION or obstruction of its BLOOD VESSELS, or an absence of BLOOD CIRCULATION. "In terms of ICAM, PLAU reportedly regulates inflammation-related signalling and exacerbates deleterious post-ischemia processes." (PMID 38082331, 2023).
lactic acidosis (1 paper, 2010). Metabolic acidosis characterized by the accumulation of lactate in the body.
leukemia (1 paper, 2026). A malignant (clonal) hematologic disorder, involving hematopoietic stem cells and characterized by the presence of primitive or atypical myeloid or lymphoid cells in the bone marrow and the blood. "Immunohistochemistry was performed to assess expression of vascular endothelial growth factor (VEGF), cathepsin G, tissue-type plasminogen activator, urokinase-type plasminogen activator, urokinase-type plasminogen activator receptor, and tissue factor in leukemia cells." (PMID 42023399, 2026).
lung squamous cell carcinoma (1 paper, 2025). "In lung squamous cell carcinoma, GATA6 has a binding site in the promoter region of plasminogen activator urokinase (PLAU), and GATA6 inhibits PLAU transcription by binding to PLAU promoter region, down-regulating PLAU expression, thereby inhibiting the cancer-promoting effect of PLAU50." (PMID 40657383, 2025).